CHRDL2 (chordin like 2)
Diseases named in the same sentence as CHRDL2 in open-access papers:
CHRDL2 is named in the same sentence as 29 diseases in open-access papers, as found by Europe PMC text mining. Sharing a sentence is not in itself a finding about the gene and the disease. The quoted sentences say what the papers report.
colon cancer (6 papers, 2014 to 2025). "CHRDL2 encodes a putative extracellular matrix protein and was shown to be over-expressed in breast, lung and colon tumors, compared with corresponding normal tissues." (PMID 24403051, 2014). "This increase in WNT signalling and modulation of BMP signalling verifies CHRDL2's role as a BMP antagonist in colon cancer cells." (PMID 40434957, 2025). "Overexpression of CHRDL2 in colon cancer cells makes them more stem‐like and resistant to chemo‐ and radiotherapy." (PMID 40434957, 2025). "Previously, CHRDL2 has been recognized as an oncogenic factor in breast cancer, lung cancer, colon cancer, and osteosarcoma, with elevated levels in tissue samples and promoting tumorigenesis." (PMID 39050472, 2024). "This is consistent with previous observations that CHRDL2 expression was increased in breast, lung and colon cancers, suggesting that CHRDL2 promotes tumorigenesis." (PMID 28009989, 2017). "First termed BNF‐1, CHRDL2 is overexpressed in breast, lung, and colon tumours." (PMID 40212011, 2025). "Although previous research has suggested that CHRDL2 may function as an oncogene in breast, lung and colon cancers, it is not yet clear how CHRDL2 promotes cancer cell proliferation and tumorigenesis in CRC." (PMID 28009989, 2017).
osteoarthritis (5 papers, 2020 to 2023). A noninflammatory degenerative joint disease occurring chiefly in older persons, characterized by degeneration of the articular cartilage, hypertrophy of bone at the margins and changes in the synovial membrane. "CHRDL2 is expressed in chondrocytes within joint cartilage and connective tissues and is associated with multiple musculoskeletal traits such as height, bone area, and osteoarthritis." (PMID 37156767, 2023). "Several of these SNVs, rs3771501 (TGFA), rs3993110 (TEAD1/DKK3), rs72979233 (CHRDL2), and rs7967762 (PFKM/WNT10B), are associated with multiple osteoarthritis joint sites." (PMID 34450027, 2021). "Of note, FRZB and CHRDL2 were recently shown to have potential protective characteristics in osteoarthritis." (PMID 33382035, 2020). "Conversely, CHRDL2 (log2FC = −2.87, P = 1.8 × 10−26) was the most significantly downregulated gene, and the gene with the largest observed fold-decrease in expression levels in high-osteoarthritis grade compared to low-osteoarthritis grade cartilage." (PMID 35088088, 2022). "Inhibitors of WNT (DKK3 and FRZB), and antagonists of BMP/TGFβ (CD109, CHRDL2, DCN FMOD, INHBA and THBS1) signalling were decreased or absent in the aged inner region, consistent with the reported upregulation of these pathways in IDD and its closely related condition osteoarthritis." (PMID 33382035, 2020).
gastric cancer (4 papers, 2022 to 2025). A primary or metastatic malignant neoplasm involving the stomach. "Clinical data on gastric cancer were evaluated for their association with CHRDL2 by using TCGA and KM-plotter databases." (PMID 36397762, 2022). "The patients with high CHRDL2 expression had worse OS, PFS, and PPS outcomes than those with low CHRDL2 expression based on the study of the clinical data for gastric cancer in the KM-plotter database." (PMID 36397762, 2022). "CHRDL2 plays a pivotal role in enabling tumor cell immune evasion in tumor microenvironment, suggesting a function of this gene in the development of gastric cancer and its immune infiltration." (PMID 36397762, 2022). "The TIMER database was utilised to create pie charts contrasting CHRDL2 expression with various immune cell types in gastric cancer." (PMID 36397762, 2022). "Patients with gastric cancer who had high expression of CHRDL2 showed worse OS, PFS, and PPS than those whose CHRDL2 expression was low." (PMID 36397762, 2022). "We identified CHRDL2, which was shown to have a role in predicting survival in patients with gastric cancer." (PMID 36397762, 2022). "The data, together with those from TCGA and the KM-plotter databases, showed that patients with gastric cancer with high level of CHRDL2 have worse prognosis than those with low expression." (PMID 36397762, 2022). "Considering the specificity of gastric cancer and the current targeted therapy, CHRDL2 and gastric cancer-related therapeutic targets were studied." (PMID 36397762, 2022). "Patients with gastric cancer with decreased CHRDL2 levels have dramatically improved OS, PFS, and PPS." (PMID 36397762, 2022). "In gastric cancer, for instance, CHRDL2 correlates with a later cancer stage and poor prognosis." (PMID 40212011, 2025). "The data suggested that CHRDL2 plays a pivotal role in the tumor microenvironment of gastric cancer and might help tumor cells evade the immune system." (PMID 36397762, 2022). "Therefore, based on these predicted pathway results, CHRDL2 affects the poor prognosis of gastric cancer by affecting cell cycle and proliferation." (PMID 36397762, 2022). "Gastric cancer development may be considerably slowed down by interfering CHRDL2 as this protein regulates cell cycle and apoptosis pathways." (PMID 36397762, 2022). "Gene set enrichment analysis showed that CHRDL2 is involved in the chemokine signaling route, the intestinal immune network, the MAPK pathway, cell cycle, and the PI3K-Akt signaling system that are associated with the pathological processes of gastric cancer." (PMID 36397762, 2022). "Therefore, CHRDL2 possibly affects the poor prognosis of gastric cancer by affecting cell cycle and proliferation." (PMID 36397762, 2022). "This study aimed to examine the role of chordin-like 2 (CHRDL2) in gastric cancer." (PMID 36397762, 2022). "In conclusion, this research demonstrated that CHRDL2 could be a biomarker of gastric cancer disease progression." (PMID 36397762, 2022). "Based on the median CHRDL2 expression, TCGA database of patients with gastric cancer was divided into two groups, namely, high and low-CHRDL2 expression groups, to further understand the relationship between CHRDL2 expression and the clinicopathological aspects of patients with gastric cancer." (PMID 36397762, 2022). "Interestingly, CHRDL2 overexpression in gastric cancer cell lines highlighted misregulation in the YAP/TAZ pathway, which is a potential method by which Chordin‐like 2 could affect gene regulation via WNT activation." (PMID 40212011, 2025). "Knockdown studies of CHRDL2 have been shown to inhibit proliferation and migration in CRC, gastric cancer and osteosarcoma, and overexpression promotes cellular proliferation, migration and clonogenicity." (PMID 40434957, 2025). "suggest that CHRDL2 can directly alter phosphorylation and activity of YAP in gastric cancer cell lines, which merits further exploration." (PMID 40434957, 2025).
gastric cancer (continued). "Another CHRD relative, chordin-like 2, has recently been suggested as a clinical biomarker that promotes cell proliferation through the YAP/TAZ pathway in gastric cancer." (PMID 38396603, 2024).
colorectal cancer (3 papers, 2017 to 2025). A primary or metastatic malignant neoplasm that affects the colon or rectum. "Chrdl2 is an oncogene that has been associated with poor prognosis in colorectal cancer cells where it is known to be an inhibitor of apoptosis." (PMID 36765634, 2023). "To determine the effects of CHRDL2 on colorectal cancer cells, we transduced four extensively characterised CRC cell lines with a virally packaged doxycycline‐inducible overexpression system for full‐length CHRDL2 cDNA." (PMID 40434957, 2025). "We filtered colorectal cancer cell lines by examining CHRDL2 levels using QRT-PCR and western blotting." (PMID 28009989, 2017). "In this study, we demonstrated that the BMP antagonist Chordin-like 2 (CHRDL2) is upregulated in colorectal cancer (CRC) tissues, and that CHRDL2 levels correlate with clinical features of CRC patients, including tumor size, TNM staging, and tumor differentiation." (PMID 28009989, 2017). "On the other hand, HCT15 (colorectal cancer), HCT116 (colon adenocarcinoma), LoVo (colon adenocarcinoma) and CaCo-2 (rectal adenosquamous) exhibited higher CHRDL2 levels." (PMID 28009989, 2017).
osteosarcoma (3 papers, 2023 to 2025). A usually aggressive malignant bone-forming mesenchymal neoplasm, predominantly affecting adolescents and young adults. "In osteosarcoma, CHRDL2 knockdown inhibited colony formation capacity and the abilities of osteosarcoma cells to proliferate, migrate, and invade in vitro." (PMID 39050472, 2024). "CHRDL2 is highly expressed in osteosarcoma tissues, and it was confirmed experimentally that CHRDL2 promotes the metastasis and proliferation of osteosarcoma cells through the BMP-9/PI3K/AKT pathway." (PMID 37404761, 2023). "Indeed, CHRDL2 has previously been shown to act via PI3K/AKT in osteosarcoma." (PMID 40434957, 2025). "CHRDL2's precise functional role in these cancers is not always clear but it has been shown to increase cellular proliferation, migration and invasion in osteosarcoma cell lines by regulation of the PI3k/AKT pathways through binding to BMP9." (PMID 40434957, 2025). "Notably, CHRDL2 has been reported to promote the proliferation and metastasis of osteosarcoma cells through the BMP‐9/PI3K/Akt signaling pathway; by binding with BMP‐9, CHRDL2 decreased BMP‐9 expression." (PMID 39050472, 2024).
breast carcinoma (2 papers, 2017 to 2024). "Although a previous study showed higher levels of CHRDL2 mRNA in breast cancer, CHRDL2's role in tumorigenesis remains largely unknown." (PMID 28009989, 2017).
colorectal adenocarcinoma (2 papers, 2017 to 2025). The most common type of colorectal carcinoma. "The expression of CHRDL2 protein was higher in colorectal adenocarcinoma and in the CRC samples than in their adjacent normal tissue counterparts (P<0.001)." (PMID 28009989, 2017). "Colorectal adenocarcinoma cell lines were deliberately chosen to encompass a range of CHRDL2 and BMP expression levels, as well as genetic mutations: CACO2 and LS180 (moderate CHRDL2), COLO320 and RKO (very low)." (PMID 40434957, 2025). "The ileocecal colorectal adenocarcinoma HCT8 and colon adenocarcinoma SW403 cell lines showed a relatively low expression of CHRDL2 while SW480 (colon adenocarcinoma), SW620 (colon adenocarcinoma) and HT29 (colon adenocarcinoma) had moderate CHRDL2 levels." (PMID 28009989, 2017).
lung carcinoma (2 papers, 2020 to 2024). "ACVR2A, ACVR1C, BMP4, and CHRDL2, on the other hand, was found to be commonly co-expressed with BMP5 in bladder, breast and lung cancer." (PMID 31973134, 2020).
endometrial cancer (1 paper, 2024). Primary or metastatic malignant neoplasm involving the endometrium (mucous membrane that lines the endometrial cavity). "Three proteins were associated with risk of prostate cancer: GP2, TSPAN1, and FLT3LG [1.29 (1.21–1.36), 1.14 (1.09–1.18), and 0.87 (0.82–0.92)] and three were associated with endometrial cancer: CHRDL2, KLK4, and WFIKKN1 [1.42 (1.21–1.65), 1.41 (1.20–1.65), and 1.42 (1.20–1.68)]." (PMID 38750076, 2024).
hepatocellular carcinoma (1 paper, 2025). A malignant tumor that arises from hepatocytes. "Mutations in genes such as CHRDL2, STC1, CTGF, GDNF, and FGF7; which are involved in liver fibrosis and inflammation were highlighted, shedding light on their potential role in advancing MASLD towards more severe stages, including liver cirrhosis and hepatocellular carcinoma (HCC)." (PMID 39927143, 2025).
rectal cancer (1 paper, 2023). A primary or metastatic malignant neoplasm that affects the rectum. "Among them, CHRDL2 and CD86 were associated with both colon and rectal cancers, with consistent direction." (PMID 37726845, 2023).
tubular adenocarcinoma (1 paper, 2022). An infiltrating adenocarcinoma in which the malignant cells form tubular structures. "Patients with HER-2-positive tubular adenocarcinoma of the stomach and low CHRDL2 expression had the best survival rates." (PMID 36397762, 2022).
cancer (7 papers, 2012 to 2025). A tumor composed of atypical neoplastic, often pleomorphic cells that invade other tissues. "CHRDL2 overexpression significantly increased the number of migrated cells (P < 0.0449), suggesting increased migratory ability, a hallmark of cancer stem cells." (PMID 40434957, 2025). "Other cancer-associated genes identified in our aCGH experiments include CHRDL2, mapped on 11q13.4." (PMID 24403051, 2014). "Our research approach combines 2D cancer cell lines engineered to inducibly overexpress CHRDL2 and 3D organoid models treated with extrinsic CHRDL2, complemented by RNA sequencing analysis." (PMID 40434957, 2025). "Through RNA‐seq analysis, we have also shown differential expression of other cancer biomarkers by CHRDL2, such as EGR1, REG4 and TFF1, which have been shown to regulate proliferation, migration and metastasis." (PMID 40434957, 2025). "RNA‐seq analysis revealed that CHRDL2 increased the expression of stem‐cell markers, WNT signalling and other well‐established cancer‐associated pathways through BMP inhibition." (PMID 40434957, 2025). "These are all well characterised processes in cancer progression as well as treatment response, highlighting CHRDL2 as an important candidate for further biomarker and therapeutic target studies." (PMID 40434957, 2025). "Analysis of TCGA database showed that CHRDL2 mRNA expression was greater in gastric cancer tumor tissues than in adjacent tissues, consistent with the results of pan-cancer study." (PMID 36397762, 2022). "The expression of CHRDL2 in pan-cancer was firstly identified through GEO database screening for differentially expressed genes." (PMID 36397762, 2022). "An increase in cytoplasmic CHRDL2 expression was found in cancer tissues compared with the surrounding normal tissues." (PMID 36397762, 2022). "Pan-cancer study revealed that CHRDL2 expression was upregulated in ESCA, GBM, KICH, PAAD, STAD, and other tumor tissues and downregulated in CESC, COAD, KIRC, KIRP, LIHC, READ, and SARC." (PMID 36397762, 2022). "Subsequent bioinformatics and database searches provided an in-depth understanding of CHRDL2's role in cancers." (PMID 36397762, 2022). "The number of cancer cell colonies was significantly increased in CHRDL2 overexpressing HCT8/CHRDL2 cells compared with control HCT8/cont cells." (PMID 28009989, 2017). "We next evaluated the effect of CHRDL2 on anchorage independent cancer cell growth (soft agar colony formation)." (PMID 28009989, 2017). "However, the role of BMP signalling in cancer, and therefore, the effect of BMP inhibition by CHRDL2 in cancer remains poorly characterised." (PMID 40434957, 2025). "Furthermore, CHRDL2 was found to differentially impact several key cancer pathways, including the EMT pathway, MYC, MTOR, PI3/AKT and RAF." (PMID 40434957, 2025). "Unravelling the pathways modulated by CHRDL2 and other BMP antagonists will undoubtedly drive future investigations in cancer research." (PMID 40434957, 2025). "In summary, our data strongly suggest that CHRDL2, by inhibiting BMP signalling and augmenting WNT signalling, promotes stem‐cell properties in cancer cells, thus contributing to cancer progression and potentially therapeutic resistance." (PMID 40434957, 2025). "In this study, we explored the impact of CHRDL2 overexpression on CRC cells to investigate whether CHRDL2's inhibition of BMP signalling intensifies WNT signalling and enhances the cancer stem‐cell phenotype and response to treatment." (PMID 40434957, 2025). "BMP7v is the only reported systemically available BMP in the context of cancer therapy and, when combined with a marked reduction in binding to endogenous BMP inhibitors such as chordin, chordin-like 2 and noggin represents a potentially significant advance in the field." (PMID 25919028, 2015).
cancer (continued). "However, CHRDL2 does not enhance proliferation and clonogenicity, suggesting that it could preferentially support cancer stem cells that are slower cycling as opposed to the hyperproliferative cancer stem cells." (PMID 40434957, 2025).
tumor (7 papers, 2017 to 2025). "Bioinformatics analysis was conducted to investigate how CHRDL2 affects tumor cell behaviour and its underlying mechanisms." (PMID 36397762, 2022). "The positive association with NK cells and CD8+ T cells suggests that CHRDL2 may enhance cytotoxic immune responses, potentially supporting anti-tumor activity." (PMID 40426943, 2025). "In vivo xenografted tumours from CHRDL2 overexpressing cells displayed increased weight and volume, with increased proliferation shown by Ki67 staining." (PMID 40212011, 2025). "The infiltration level of most immune cells, including Treg, Th2, Th1, and Th17 cells, was correlated with CHRDL2, and this association was examined to further understand the effect of CHRDL2 on the tumor microenvironment (TME)." (PMID 36397762, 2022). "Regarding DFS, the univariate and multivariate analyses revealed that tumor diameter, TNM stage, histologic type, and tumor CHRDL2 expression were independent prognostic factors." (PMID 28009989, 2017). "Our immunohistochemistry results showed that CHRDL2 increased the expression of ki67 and cyclin D1, which were tumor proliferation markers." (PMID 28009989, 2017). "CHRDL2 mRNA upregulation has been observed in colon, breast, liver and prostate cancer and high levels predict poor prognosis and correlate with increased tumour size and later TNM stages." (PMID 40434957, 2025). "Consequently, we also explored the impact of CHRDL2 overexpression on normal ISCs within an organoid model, aiming to shed light on the role of CHRDL2 in tumour initiation." (PMID 40434957, 2025). "Even in interface areas, CHRDL2 was still overexpressed in tumor areas compared with normal areas." (PMID 28009989, 2017). "Patient survival studies have shown CHRDL2 overexpression predicts poor prognosis in CRC patients, and mRNA expression is elevated in patient tumour tissues compared to a control." (PMID 40434957, 2025). "Consistent with the findings of several other studies, the present study showed that CHRDL2 was expressed in ESCA, GBM, and KICH and upregulated in PAAD, STAD, and other tumor tissues." (PMID 36397762, 2022). "Meanwhile, CHRDL2 expression was downregulated in CESC, COAD, KIRC, KIRP, LIHC, READ, SARC, and other tumor tissues." (PMID 36397762, 2022). "High CHRDL2 levels correlated with larger tumor size (P<0.01), later TNM staging (P<0.01), and poor tumor differentiation (P<0.01)." (PMID 28009989, 2017). "Having demonstrated in vitro that CHRDL2 enhanced CRC cell growth, we next CHRDL2 affected in vivo xenograft tumor growth of CRC HCT116 and HCT8 cells." (PMID 28009989, 2017). "The univariate analysis revealed that tumor diameter, TNM stage, histologic type, and tumor CHRDL2 expression were prognostic indicators for OS, while multivariate analysis excluded depth of infiltration." (PMID 28009989, 2017). "Furthermore, high CHRDL2 levels correlate with clinical features, including tumour size, TNM staging, and tumour differentiation." (PMID 40212011, 2025). "Although not previously reported in MASLD, CHRDL2 is upregulated in a range of tumor tissues including HCC49, while STC1, CTGF50, GDNF and FGF7 are all linked to hepatic fibrogenesis." (PMID 37903863, 2023). "Moreover, CHRDL2 levels correlated with clinical features, such as tumor size, TNM staging, and tumor differentiation, and all of these parameters were independent factors for CRC survival." (PMID 28009989, 2017).
CHRDL2 also shares sentences with these, for which no sentence is quoted: adenocarcinoma (1 paper); autoimmune disease (1); cervical cancer (1); colon adenocarcinoma (1); coronary artery disease (1); diabetes (1); Hypertension (1); leiomyoma (1); leukoplakia (1); lymph node metastasis (1); osteoporosis (1); progeroid syndrome (1); prostate carcinoma (1); reproductive system diseases (1); stomach cancer (1).